IL6 (interleukin 6)
Diseases named in the same sentence as IL6 in open-access papers (continued):
Sharing a sentence is not in itself a finding about the gene and the disease.
Sepsis (continued). "The blood glucose level of patients with sepsis was positively correlated with the levels of IL-6, TNF-α, and IL-1β and was negatively correlated with the levels of CD4+/CD8+." (PMID 35664433, 2022). "ROC curve analysis revealed that the diagnostic value of plasma WBC, CRP, and TNF-α for sepsis was dissatisfactory, while PCT and IL-6 were slightly better." (PMID 36402943, 2022). "M3 was also protective in mice with CLP-sepsis, measured by decreased levels of serum AST, ALT, TNF-α and IL-6, and attenuated severity of sepsis-associated acute lung injury." (PMID 35784361, 2022). "Our results showed that the W/D weight ratio of lung tissue in rats with sepsis was significantly reduced by the neutralization of IL-17A, as well as the content of inflammatory factors, such as IL-6 and TNF-α." (PMID 36253831, 2022). "Serum samples were also analyzed for changes in glucose, urea, creatinine and IL-6 levels, which are commonly used markers of murine sepsis; these were all altered in WT-infected mice." (PMID 36045589, 2022). "During sepsis, miRNAs were observed to be mainly involved in the activation of TLR-4, leading to the production of pro-inflammatory cytokines (IL-6, IL-1, TNF) that cause endothelial dysfunction and organ damage." (PMID 36012630, 2022). "During sepsis, elevated cytokines (tumor necrosis factor-alpha, interleukin-6, interleukin 1 beta) alters sympathovagal balance." (PMID 35572539, 2022). "Several anti-IL-1β and anti-IL-6 agents have also been developed and clinical data also demonstrate their beneficial effects against sepsis." (PMID 35337084, 2022). "During the pathological progress of sepsis, several inflammatory cytokines such as IL‐1β, IL‐6, TNF‐α and IFN‐γ are excessively produced." (PMID 35502484, 2022). "In various animal models of sepsis, IL-6 and TNF-α expression were significantly elevated compared to the normal group." (PMID 36685507, 2022). "Cytokine adsorbers have been used to treat sepsis or ALI by reducing the levels of cytokines such as IL-6, IL-1β and TNF-α11,18–20." (PMID 35882835, 2022). "Administration of 3MA (an autophagy inhibitor) attenuated IL6 and TNFa production as well as sepsis symptoms in a lethal model of murine sepsis." (PMID 36387896, 2022). "Sepsis related to IE is accompanied by local and strong systemic inflammatory response with elevated circulating IL-6, IL-2R and IL-1β concentrations." (PMID 36233404, 2022). "In particular, IL-6, IL-8, and IL-10 are used to diagnose sepsis, to assess the level of inflammatory response and to help the prognosis." (PMID 36291031, 2022). "LPS administration in mice is a widely used animal model to study sepsis, which partially mimics some of the initial clinical features in humans, including the serum increases of pro-inflammatory cytokines, such as TNFα, IL-6 and IL-1b." (PMID 35887265, 2022). "The expression level of TREM-1, TNF-α, and IL-6 in the sepsis model showed a consistent expression trend in sepsis patients." (PMID 36110326, 2022). "On the contrary, miR-483-5p and miR-497-5p resulted in aggravating pulmonary disease induced by sepsis since their overexpression determined an increased production of TNFα, IL1β and IL6, thus promoting inflammation." (PMID 36012630, 2022). "Two pro-inflammatory mediators, IL-6 and IL-10, have been specifically identified as being involved in the development of renal lesions in murine models of sepsis." (PMID 37675005, 2022). "IL-6 was a cytokine secreted by the body in the early stage of sepsis, which played an important role in development and prognosis of septic patients." (PMID 36160407, 2022). "In Spearman correlation rank analysis, IL-6 was positively correlated with IL-10 (r = 0.654, p < 0.001), in which G- sepsis patients showed a stronger linear correlation between the two cytokines." (PMID 36544765, 2022).
Sepsis (continued). "IL-6 levels have been discovered to be elevated in critical conditions including sepsis and ARDS, and studies have demonstrated that it plays a key role in the disease's progression." (PMID 36452899, 2022). "Bacteremia and subsequent endotoxemia directly stimulate the release of inflammatory cytokines, including TNF-α, IL-1β, IL-6, IL-12, and IL-18 in sepsis." (PMID 36120368, 2022). "For instance, many animal studies and clinical trials with sepsis patients tend to focus on a limited number of readouts, including IL-6 plasma levels as a parameter of inflammation, or biomarkers indicating dysfunction of a single organ." (PMID 35634305, 2022). "The EVs containing histones released by mouse-derived BMDM interact with TLR4, displaying pro-inflammatory effect, which can promote the production of TNF, IL-6 and IL-1β, thereby increasing the lethality of sepsis." (PMID 35463634, 2022). "TNF-α can induce the expression of IL-6, IL-10, and IL-18, which can be used as an inflammatory marker for the development of sepsis." (PMID 35698642, 2022). "Wild–type mice exhibited rapid induction of TNF–α and IL–6 in the early stage of sepsis and a significant decrease in TNF–α and IL–6 levels thereafter and increased production of antiinflammatory IL–10 cytokine in the LPS model." (PMID 35911737, 2022). "Almost all G- sepsis patients experience a marked elevation of IL-6 compared to IL-10 at admission, which was less commonly observed in the G+ sepsis group." (PMID 36544765, 2022). "We evaluated 8 cytokines and 8 adipocytokines in both sepsis and burns and concluded that resistin forms a network with IL-6, IL-8, IL-10 and MCP-1 by hierarchical clustering analysis based on Spearman correlation." (PMID 35784283, 2022). "In OPN-/- mice, increase of these cytokines was in general moderate, with a significant decrease of IL-1β and IL-6, in line with the mild sepsis developed by these mice." (PMID 36119089, 2022). "Ca2+ was found to be significantly associated with high levels of proinflammatory cytokines (e.g., TNF-α and IL-6) and procalcitonin in severe sepsis." (PMID 35711261, 2022). "IL-6, another proinflammatory cytokine, is also involved in the pathogenesis of sepsis and is considered to be a better predictor of sepsis than TNF-α." (PMID 34757596, 2022). "Withinthe large number of biomarkers for sepsis diagnosis, around interleukin-6 (IL-6) is one withthe best sensitivity and specificity." (PMID 36198198, 2022). "Gold nanoparticles (AuNPs) conjugated with antibody-targeting IL6 were used on paper for the detection of sepsis based on the density of AuNPs binding on the paper immobilized with antibody capturing IL6." (PMID 35624657, 2022). "A previous study has confirmed that the immunomodulatory treatment of Afelimomab exerts a protective effect in patients with severe sepsis only when the concentration of IL-6 exceeds the threshold of 1,000 pg/ml." (PMID 35185571, 2022). "The diffuse inflammation resulting from sepsis is responsible for a renal toxicity of the immune response, via pro-inflammatory cytokines (IL-6, IL-10, IL-1β, TNF-α) and a monocytic infiltration of renal parenchym." (PMID 37675005, 2022). "In the infected group, there was a positive correlation between IL-17 levels and IL-8, but in the sepsis group, there was a positive correlation between IL-6 and IL-8, showing that IL-17 is better able to react to inflammation markers." (PMID 35937269, 2022). "For G- sepsis patients, the observed narrower confidence intervals (compared to G+ sepsis patients) in “IL-6 and IL-10 differences” proved the efficacy of using such indicator to describe the IL-6–IL-10 correlation." (PMID 36544765, 2022). "In this regard, IL-6 is one of the first cytokines released during inflammation, including the sepsis hyperinflammatory cascade." (PMID 36552833, 2022).
Sepsis (continued). "When contrasting with the sepsis group, the 10 mg/kg Montelukast pre-treated group showed considerably lower expression of inflammatory markers IL-6 and IL-1B." (PMID 35928365, 2022). "As expected, such changes ultimately led to proinflammatory cytokine production during late-stage sepsis (IL-1β, IL-6, IFNγ, TNFα)." (PMID 35349828, 2022). "Although intensive crosstalk between inflammation and coagulation has been well-described for sepsis, less is known about the impact of IL-6 on coagulopathy and transfusion requirements in major trauma." (PMID 34073768, 2021). "TNF-α, IL-6, IL-12 and IL-1β play an important role in sepsis, and levels of TNF-α are negatively correlated with survival in septic patients." (PMID 33995024, 2021). "The present study, which compared patients with sepsis alone vs. sepsis and ARDS, identified much higher levels of serum FGF21 and pro-inflammatory factors (PCT, CRP, IL-6, and TNFα) in the Sepsis + ARDS group." (PMID 34154595, 2021). "Reduced cytokine levels in sepsis, prevented acute lung injury and organ dysfunction, down‐regulated inflammation (IL‐10, IL‐6) and swiftly up‐regulated phagocytosis and bacterial killing." (PMID 34766151, 2021). "Little has previously been known about the prognostic value of IL-6 in neonates suspected of sepsis." (PMID 33407770, 2021). "Previous study has found that HT can inhibit the expression of inflammatory factors such as TNF-α, IL-1β and IL-6, and attenuate infiltration of activated immune cells in LPS-mediated sepsis in mice." (PMID 34858184, 2021). "Given this context, the statistically distinct reduction of IL-6 by βS supports the potential usefulness of βS in sepsis-induced inflammation." (PMID 33997001, 2021). "Conclusions and Relevance: IL-6 plasma concentration was elevated in critically ill MIS-C patients but at levels much lower than those of sepsis." (PMID 34869111, 2021). "CRP is an acute-phase protein synthesized by the liver, induced by cytokines like IL-6, and its level in the blood increases within hours in response to inflammation and sepsis." (PMID 34205667, 2021). "Elevated levels of plasma IL-6 were observed 12 h after induction (P = 0.018); plasma ET-1 concentration increased significantly at 24 h of sepsis." (PMID 34815465, 2021). "Gene co-expression analysis across the 124 sepsis cohorts showed that IL6 gene expression was directly correlated to MYD88 (r = 0.26, p = 0.004) and NFKB1 (r = 0.19, p = 0.039) transcript levels." (PMID 34183713, 2021). "Stimuli for excessive AVP release during inflammatory states includes an increased plasma concentration of interleukin-6, particularly during sepsis and tissue injury from trauma." (PMID 34268347, 2021). "The observed cytokines correlate to inflammatory markers as predictors for sepsis severity and mortality (e.g., IL-6, IL-8, MIP-1α or IL1ra)." (PMID 34944644, 2021). "It provided a fast method for detecting the concentration of IL-6 in human serum albumin by an optical sensor, which contributes to diagnosing sepsis quickly in clinical." (PMID 34281552, 2021). "In some reports, plasma IL-6 levels after sepsis are essential mediators of mortality and morbidity due to sepsis in mice and humans." (PMID 33946773, 2021). "By contrast, different cytokines participate in sepsis progression, with increased levels of IL-1β, IL-6, IL-8, IL-12, IFN-γ, granulocyte colony-stimulating factor, and TNF-α observed in non-survivors as compared to survivors." (PMID 34884813, 2021). "IL-6 concentrations under physiological conditions are very low (1–5 pg/mL) but in inflammation and sepsis they can reach high nanomolar range." (PMID 33670858, 2021). "NLR and IL-6 are both clinically accessible biomarkers which are closely related to the occurrence and development of sepsis." (PMID 33796105, 2021). "The pooled sensitivity, specificity, and AUC of IL-6 for the diagnosis of sepsis were 0.72 (95% CI, 0.65–0.78), 0.70 (95% CI, 0.62–0.76), and 0.77 (95% CI, 0.73–0.80), respectively." (PMID 33902476, 2021).
Sepsis (continued). "For example, lnc‐KCNQ1OT1 negatively regulates inflammatory factors (including TNF‐α, IL‐1β, and IL‐6) in sepsis‐induced myocardial injury and intimal hyperplasia." (PMID 34761437, 2021). "Trans signaling by soluble IL-6 receptors can only be achieved at very high circulating concentrations of IL-6 (ng/mL range) observed in septicemia and cytokine release syndromes." (PMID 33921604, 2021). "In this regard, several reports have shown that IL-6 is a useful biomarker for detecting early sepsis; however, CRP and PCT are still often within the reference range owing to their much slower rates." (PMID 34749673, 2021). "In our study, the animals with sepsis developed proinflammatory profiles that were characterized by increased expression of IL-1β, IL-10, IL-6 and TNF-α." (PMID 33676566, 2021). "For example, netrin-1 protected against acute lung injury sepsis in rats through decreasing the expression of IL-1, IL-6, and TNF-α, and in a porcine model of acute lung injury, through ameliorating TNF-α, IL-1β, IL-6 and IL-8." (PMID 35250531, 2021). "A number of studies have reported that an excessive productions of TNF-α, IL-6, and IL-8 severely enhances myocardial dysfunction during sepsis." (PMID 33819192, 2021). "The levels of the proinflammatory cytokines TNF-α, IL-1β, IL-6, IL-12p70, and IL-10 in the serum and in the lungs of the A. baumannii-derived sepsis mouse model treated with IOX1 were significantly reduced." (PMID 33536477, 2021). "Cytokine storm is closely related to the initiation and progression of sepsis, and the level of IL-6 is positively correlated with mortality and organ dysfunction." (PMID 35118141, 2021). "Nevertheless, IL-1β and IL-6 were elevated in the hippocampus at P2 and P30 and in the neocortex at P8 and P30 in mice from the sepsis group." (PMID 33632243, 2021). "This generated immune response sometimes exacerbates the expression of cytokines, such as IL6, which was observed during inflammation and other disease conditions, including sepsis and influenza." (PMID 35126382, 2021). "While levels of IL-6 and IL-10 strongly increased in control patients, patients with postoperative sepsis were unresponsive to LPS stimulation, hinting towards sepsis-induced cellular anergy at the time of study inclusion." (PMID 33939725, 2021). "Multiple reports indicate that IL-6 is an excellent biomarker of severity and a prognostic indicator in patients with sepsis." (PMID 33736691, 2021). "Combinations of LBP A + IL-6 A +TLR B and LBP B + IL-6 A +TLR A were regarded to be a high risk for sepsis (p<0.006 and p=0.012, respectively), but the proportion of patients was low (4.2% and 4.8%, respectively)." (PMID 34295331, 2021). "Our study showed that the levels of NLR and IL-6 were significantly higher in the deceased patients with sepsis." (PMID 33796105, 2021). "The levels of inflammatory cytokines IFN-gamma and IL-6 were significantly reduced in mice with CLP-induced sepsis when receiving rSj-Cys-treated BMDMs compared with sepsis mice receiving untreated BMDMs or PBS control." (PMID 33718268, 2021). "In dogs and other animal models, IL-6 increased within the 1st h after induction of sepsis and peaked after 4 h in dogs." (PMID 34222394, 2021). "In summary, our data show that IL-6 plasma concentration was elevated in critically ill MIS-C patients but at levels much lower than those of sepsis." (PMID 34869111, 2021). "In sepsis, EC activation induced adhesion receptors and released inflammatory mediators, such as interleukin (IL)-1, IL-6 and tumor necrosis factor." (PMID 33482737, 2021). "Among the three biomarkers, neutrophil CD64 has the highest diagnostic value for sepsis in adult patients, followed by PCT and IL-6." (PMID 33902476, 2021). "In a study conducted on patients with sepsis and acute lung injury, hemoperfusion reduced IL-1, IL-6 and IL-8 levels." (PMID 34490065, 2021).
Sepsis (continued). "Collectively, accumulating evidence indicates that the inhibition of IL-6 trans-signaling is a promising therapy for sepsis." (PMID 34253862, 2021). "Studies have implicated that overproduction of IL-1β, IL-6, TNF-α, and IL-10 in mice and humans is associated with sepsis, and IFN-γ expression is enhanced persistently in patients who die of sepsis." (PMID 34612675, 2021). "The level of PCT was positively correlated with IL-6 only in the sepsis group and CRP only in the infection group." (PMID 34745113, 2021). "Interleukin-6 (Il6), known as a classical pro-inflammatory cytokine in sepsis, is a typical tolerizable gene." (PMID 34712224, 2021). "In animal models of sepsis, treatment with serine protease inhibitors (bikulin and ulinastatin) reduces TNFalpha, IL-6 and a multitude of other inflammatory mediators." (PMID 35058867, 2021). "More importantly, N protein aggravates lung injury, accelerates death in sepsis and acute inflammation mouse models, and promotes IL-1β and IL-6 activation in mice." (PMID 34341353, 2021). "IL-6 is remarkably correlated to the severity of sepsis and the clinical trial of its receptor antagonists is currently underway in children's severe sepsis (NCT04850443)." (PMID 35118141, 2021). "This explains a significant increase in Tnf-α, Ifn-α, IL-1β, and IL-6 mRNAs in the LPS stimulated spleen, liver, and kidney and demonstrates the effective suppression of these key sepsis markers by MIC-1." (PMID 33793581, 2021). "The diagnostic performance of progranulin to differentiate between sepsis and the distractors was comparable to that of procalcitonin, and generally better than the proinflammatory markers C-reactive protein and interleukin-6." (PMID 34476621, 2021). "In an observational study, we measured heparin-binding protein (HBP), myeloperoxidase (MPO), IL-6 and IL-8 in 167 sepsis patients on intensive care unit admission." (PMID 33461369, 2021). "The development of a PFO antitoxin and cytokine-targeted therapies using an anti-IL-6 antibody should be considered for the treatment of patients with C. perfringens sepsis with MIH." (PMID 34385995, 2021). "Several biomarkers (e.g., CRP, procalcitonin, WBC and differential counts, lactate, and interleukin-6) had already been investigated for their role of sepsis-related fatality." (PMID 34829326, 2021). "Pellino1−/− mice suppressed the protein expression of Pellino1, TRAF6 and NF-κB and inhibited the levels of TNF-α, IL-6, IL-1β and IL-18 in mice of sepsis." (PMID 33632252, 2021). "We focused principally on monocyte TNFα production because of its crucial role in the inflammatory cascade and data linking reduced monocyte TNFα release to survival following sepsis, although a similar pattern was observed with IL6." (PMID 34825153, 2021). "We determined the plasma levels of interleukin-6 (IL-6; a relatively early biomarker in sepsis) and endothelin-1 (ET-1; a marker of tissue hypoxia) to confirm and characterize the course of pro-inflammatory processes in the animals." (PMID 34815465, 2021). "More severe lung damage was observed in patients with ARDS than in the healthy control and sepsis groups, which was accompanied by higher neutrophil numbers and higher serum levels of the inflammatory cytokines IL-6 and IL-8 in ARDS patients." (PMID 34336711, 2021). "Several reports have demonstrated that TNF-α, IL-6, and IL-10 can serve as both makers and mediators of sepsis severity and that elevated cytokine levels predict mortality following CLP." (PMID 35003518, 2021). "Since the IL-6 is crucial for the progression of acute inflammatory diseases, such as sepsis, this cytokine represents an important molecule within the LPS-signaling cascade." (PMID 34944023, 2021). "In terms of combinations of LBP, IL-6 and TLR, LBP A + IL-6 B +TLR A is a low-risk combination of severe sepsis (p=0.027)." (PMID 34295331, 2021).